CD28 (CD28 molecule)
Diseases named in the same sentence as CD28 in open-access papers (continued):
Sharing a sentence is not in itself a finding about the gene and the disease.
tumor (continued). "Furthermore, tumor cells can escape the anti-cancer immunity by activating regulatory T lymphocytes that express cytotoxic T-lymphocyte-associated protein 4 (CTLA-4) competing with CD28 of effector T lymphocytes for binding to CD80/CD86 of antigen presenting cells." (PMID 32610582, 2020). "The PD-1/PD-L1 signaling axis dampens TCR and CD28 signaling in T cells and is hijacked by PD-L1 expressing tumor cells to deactivate antitumor responses." (PMID 32983966, 2020). "Insufficient CD28 stimulation within the TME combined with tumor cell expressing factors, such as PD-L1 and CD95, is also closely linked to deletion of effector T cells through a process known as tolerance." (PMID 33008037, 2020). "Again, this aligns well with our data and supports the concept that differentiated memory T cells in tumours utilise CD28." (PMID 33223527, 2020). "MC-CAR T cells had superior effector function as judged by their ability to expand and retain their cytolytic activity after repeated exposure to tumor cells in comparison with CD28- or 41BB-CAR T cells." (PMID 33148882, 2020). "Clinical data mirrors preclinical findings: CD28 supports strong but short-lived anti-tumor efficacy." (PMID 32429316, 2020). "Because the hybridoma cells used as recipients in our transfection experiments are tumor cells, it is possible that they expressed abnormally elevated levels of ER chaperones that facilitated expression of YT/LL CD28." (PMID 32765524, 2020). "In comparison, CD28-expressing CAR-T cells have more IL-2 secretion that gives rise to faster tumor eradication." (PMID 33167514, 2020). "In preclinical studies, the presence of ICOS drives CAR-T-cells into a TH17/TH1 differentiation state characterised by increased IL-17 and IL-22 production, enhanced persistence and improved anti-tumour function compared with CD28 or 41BB." (PMID 32824734, 2020). "These specialized DCs internalize and cross-present tumor antigens to T cells and induce a CD28-dependent proliferation of tumor-specific T cells, which regulates the strength of the immune response." (PMID 32932620, 2020). "T cells were engineered to have the ability to attack tumor cells by generating CAR constructs consisting of genes encoding scFv, a co-stimulatory domain (CD28 or TNFRSF9), and CD247 signaling domains for T cell proliferation and activation." (PMID 32050611, 2020). "Although the mechanistic signaling pathways remain elusive, FAK inhibition induced tumor regression of CD80-expressing tumors by increasing the CD28+ T cell population within the TME." (PMID 32514188, 2020). "These cells synthesize a protein on the T-cell surface binding to the surface proteins of the tumor cell (e.g., CD19 or CD28), which then acts as a reprogrammed killer T cell after binding to the tumor cell." (PMID 33126715, 2020). "MC-CAR T cells proved the most efficacious against 2 EphA2-positive tumor cell lines, expanding more and retaining their cytolytic capacity significantly longer than CD28 or 41BB." (PMID 33148882, 2020). "Using logistic regression analyses, we revealed the independent predictive value of the CD8+CD28+ T-cell count for early tumor response to SABR." (PMID 30971280, 2019). "As an essential co-stimulatory molecule, CD28 on CD8+ T cells interacts with B7 molecules on antigen-presenting cells to activate the anti-tumor immune response of CD8+ T cells to tumor antigens." (PMID 30971280, 2019). "Our investigation did identify an additional factor, the pre-SABR CD8+CD28+ T-cell count, as predictive of early tumor response to SABR." (PMID 30971280, 2019). "We isolated MDSC populations from spleen and tumors to set up a co-culture with anti-CD3/CD28 mAb-activated T cells from tumor-free mice, and used monocytes and granulocytes isolated from spleens of tumor-free mice as controls." (PMID 31694706, 2019).
tumor (continued). "For example, CD27-based second-generation CAR T cells displayed similar anti-tumor efficacy in a xenograft mouse model of ovarian cancer in direct comparison to CD28- or 41BB-containing CAR T cells." (PMID 31108883, 2019). "Meanwhile, tumor immune-related pathways were also enriched, such as B cell development pathway, cd28 signaling in T Helper cell, chemokine signaling, IL-1 signaling, IL15 signaling, IL-2 signaling, IL-3 signaling, IL-4 signaling, and IL-8 signaling." (PMID 31258820, 2019). "The deletion of the Lck binding moiety in the CD28 CAR endodomain of a CD28-CD3ζ signaling CAR can enhance the anti-tumor efficacy in the presence of Treg cells." (PMID 31835562, 2019). "In agreement with previous data, only T cells armed with signalling UniCAR CD28/ζ constructs were able to effectively eradicate tumor cells in the presence of the His-tagged or un-tagged TM." (PMID 31332252, 2019). "New promising indicators of response to ICIs, such as the post-pembrolizumab fold-change of Ki67+ PD-1+ CD8 T cells relative to tumor burden, CD28 expression on CD8 T cells will be considered in future analyses." (PMID 30867072, 2019). "Specifically, M1 macrophages were distinguished by higher expression of CD80—a costimulatory molecule that signals through CD28 to amplify T cell activation and contributes to anti-tumor immunity." (PMID 31552039, 2019). "The CAR-T cells demonstrated superior in vivo persistence and anti-tumor effects in models of hematologic malignancies as compared with CAR-T cells expressing a CD28 or 4-1BB co-stimulatory domain alone." (PMID 31766350, 2019). "It has been described that CD28, as a costimulatory domain, supports stronger T cell expansion and improved tumor eradication, whereas 4-1BB, as a costimulatory domain, is associated with prolonged persistence and ameliorates the development of exhaustion." (PMID 31835562, 2019). "Each tumor-infiltrating Treg cells or peripheral Treg cells was co-cultured with peripheral CD8+ T cells with αCD3/CD28 stimulation." (PMID 31801611, 2019). "This modification, which separates signaling through CD3zeta from CD28 co-stimulation, allows the increased on-tumor specificity in situations where a unique tumor target is unavailable." (PMID 31783836, 2019). "Our results suggest that the pre-SABR CD8+CD28+ T-cell count predicts early tumor response to SABR in patients with lung metastases from NSCLC independently." (PMID 30971280, 2019). "The CD8 T cells were labeled before co-culture with carboxyfluorescein succinimidyl ester (CFSE) and were stimulated in the presence of the tumor-associated B cells with anti-CD3- and anti-CD28-coated magnetic dynabeads for 48 hours." (PMID 31671149, 2019). "Globally, the reduced CD28 availability increases the activation threshold of T-cells, thus dampening the recognition of tumor antigens." (PMID 31581738, 2019). "We showed the existing correlation between increased peripheral CD8+CD28+ T cells and prolonged survival in ADs, which is consistent with the anti-tumor function of CD8+CD28+ T cells." (PMID 31623615, 2019). "According to multivariate logistic analyses, the CD8+CD28+ T-cell count predicted a 1-month tumor response to SABR (OR 0.19, 95% CI 0.04–0.90; P = 0.037) independently." (PMID 30971280, 2019). "The results showed that only CD8+CD28+ T-cell counts independently predicted early tumor response 1 month after SABR with statistical significance (OR 0.19, 95% CI 0.04–0.90; P = 0.037)." (PMID 30971280, 2019). "Most of the T cells were activated and expanded ex vivo via cytokine and anti-CD3/CD28 or tumor specific-antigen-dependent stimulation followed by adoptive transfer to tumor patients." (PMID 31024913, 2019). "Recently, third-generation CAR T-cells have been produced by incorporation of both the CD28 and 4-1BB co-stimulatory signals, expecting to obtain good anti-tumor potency and prolonged persistence at the same time." (PMID 31824840, 2019).
tumor (continued). "The infiltration of CD4+ Treg cells into solid tumors can decrease the anti-tumor activity of CD28-CD3ζ signaling CART cells." (PMID 31835562, 2019). "Collectively, this data indirectly illustrates the higher number of infiltrating T-cells within the tumor microenvironments of HPV+ HNSCC through the identification of significantly higher levels of the constitutively expressed T-cell-specific CD28 marker." (PMID 31394808, 2019). "CD28 is a co-stimulatory molecule that is required for CD8+ T cells to develop an anti-tumor response." (PMID 30971280, 2019). "Whereas, the co-expression of PD-1 and CD28 confers an exhausted phenotype and a defective anti-tumor functionality, reversible by PD-1 blockade." (PMID 30400835, 2018). "It has been pointed that CD28 can enhance the telomere length, which can affect the persistence and anti-tumor efficacy of T cells." (PMID 29568411, 2018). "Due to the repression by the critical immune checkpoint (IC) target PD-1, an understanding of CD28 regulation of tumor T cells would greatly aid in reinvigoration strategies with PD1/PDL1-based immunotherapies." (PMID 30400835, 2018). "In vivo animal studies further revealed enhanced persistence and anti-tumor responses of CD4+ CAR T cells in case of ICOS based CARs in contrast to the CD28 or 4-1BB containing CARs." (PMID 30713539, 2018). "As expected, the addition of autologous Tregs suppressed the activation of tumor antigen-reactive T cells (CD3+/CFSElow/IFNγ+) in anti-CD3/anti-CD28-activated aMILs stimulated with tumor antigen-pulsed autologous BM." (PMID 29467463, 2018). "This suggests that the use of anti-CD3/anti-CD28 beads in our protocol provides sufficient stimulation to enable expansion of TILs from tumours with low CD3+ infiltration." (PMID 30039427, 2018). "As such, there were barely any undifferentiated naïve (CD45RA+CD27+CD28+) T cells in the lung or tumor." (PMID 30505306, 2018). "Recently our group demonstrated that CD8+CD28-CD127lowCD39+ regulatory T lymphocytes, previously found highly concentrated within tumor microenvironment, circulate with elevated frequency in the peripheral blood of HIV infected patients." (PMID 30459765, 2018). "CAR-T cells with CD28 or 4-1BB signaling domain have shown potent anti-tumor efficacy in vivo for B cell malignancies." (PMID 29568411, 2018). "Specific tumor cell lysis by CAR+ γδT cells was equivalent to that observed with CD3/CD28+-stimulated GD2-CAR+ αβ T cells." (PMID 29310916, 2018). "Remaining pathogen and tumor reactivity of CD28-blocked donor T-cells need to be investigated in further studies using haploidentical murine transplantation models." (PMID 28979262, 2017). "We found that CD3/CD28 Dynabead T cells mediated a greater anti-tumor response when mice were treated via intravenously infusion of CD19 CAR RNA-transferred T cells." (PMID 28523432, 2017). "We found that these tumor-infiltrating CD8+ T cells were able to suppress the proliferation of responder T cells after anti-CD3/CD28 stimulation." (PMID 28806909, 2017). "In this context, the CD28 aptamer worked as an adjuvant to stimulate a stronger immune response after tumor vaccination." (PMID 28325295, 2017). "CARs that activate through chimeric CD28 or CD137 endo-domains have anti-tumor activity and have facilitated durable remissions in clinical trials, with pros and cons for each design." (PMID 27548616, 2016). "The aptamer-P60 chimera binds to CD28-expressing lymphocytes inhibiting Foxp3 in the T-cell compartment and enhancing the immune response elicited by a tumor-antigen vaccination." (PMID 27783034, 2016). "A CD28 score of the tumor greater than or equal to 1 was observed in 126 of 191 patients, and these patients were considered to have high expression." (PMID 26918337, 2016). "The MRP1 aptamer was used to generate a bi-specific MRP1-CD28 aptamer, which was used to create a CD28Aptvax (irradiated tumor cells coated with CD28 agonistic aptamer)." (PMID 26992239, 2016).
tumor (continued). "With the use of the MRP1 aptamer we engineer a MRP1-CD28 bivalent aptamer that is able to bind MRP1-expressing tumors and deliver the CD28 costimulatory signal to tumor-infiltrating lymphocytes." (PMID 26992239, 2016). "Tumor-associated CTLA-4 has been shown to inhibit anti-tumor T cell immunity by interacting with CD28 expressed on T cells to induce tumor-specific T cell apoptosis or by impairing cytokine production and T cell-mediated cytotoxicity." (PMID 27050369, 2016). "Target: TNF-alpha inhibitor.Mechanism of action:Increases tumor cell apoptosis:–Enhancing IL-10Induces G0-G1 cell cycle arrest:–CDK2 inhibition.T- cells activated via B7 pathway:–Tyrosine phosphorylation of CD28." (PMID 27119356, 2016). "We have previously shown that CD28 agonistic aptamers are able to costimulate T lymphocytes and promote tumor immunity when used as adjuvants in tumor-antigen vaccination." (PMID 26992239, 2016). "We have recently generated a CD28 agonist aptamer that was proved to potentiate the antitumor immune response induced in tumor-specific antigen vaccination, enhancing tumor-bearing mice survival." (PMID 26992239, 2016). "In line with this, short-term culture of tumor digests with IL-2 revealed a heterogeneous expression of CD28 on CD103+ and CD103- TIL." (PMID 27650547, 2016). "The authors demonstrated that anti-tumor activity of CD28-CD3ζ CAR-T cells in the presence of Treg cells was less than that of CD3ζ-CAR-T cells against tumor CEA-overexpressing tumors." (PMID 26999211, 2016). "The median tumor CTLA-4 score was 2, the median lymphocyte CTLA-4 score was 0.7, the median tumor CD28 score was 1, and the median lymphocyte CD28 score was 0.7." (PMID 26918337, 2016). "PBMCs required addition of lipopolysaccharide (LPS) and interferon-γ (IFN-γ) or anti-CD3/anti-CD28 beads, i.e. immune cell activation, to reduce tumor spheroid size." (PMID 25871398, 2015). "As anticipated, we observed high expression of CD38 (>90%) and CD184 (>70%) in tumor cells from both patients however, CD28 expression was observed in <10% of gated tumor cells from either patient." (PMID 25853860, 2015). "It is also conceivable that the in vitro stability of RPCI-WM1 cells was ultimately established from a CD28+ tumor clone, which was present as only a minority fraction in the index patient." (PMID 25853860, 2015). "The intended mechanism of action of AGS-003 is to induce CD8+ CD28+ CD45RA− CTLs against patient-specific tumor antigens." (PMID 25901286, 2015). "CARs containing 4-1BB or both CD28 and 4-1BB have also showed superior in vivo expansion and anti-tumor efficacy compared to CARs carrying CD28." (PMID 26700307, 2015). "The addition of 4-1BB as a second co-stimulatory molecule in the 2G CD28 CAR construct rendered more potent in vivo tumor responses." (PMID 26700307, 2015). "CD4+ CD25lo Tconvs were sorted from lymphoid tissue and co-cultured in the presence of anti-CD3 and anti-CD28 beads with either CD69+ or CD69− Tregs sorted from tumor draining or non tumor draining lymph nodes, at varying Tconv : Treg ratios." (PMID 26433463, 2015). "Concerning the activation of T cells, it is known that B7.1 is required as a co-stimulatory signaling molecule and that binding of B7.1 to CD28 facilitates adhesiveness between lymphocytes and tumor cells." (PMID 24608380, 2014). "In another strategy, microsized polystyrene beads coated with tumor antigen-specific peptide–MHC complexes, anti-CD28 and anti-4-1BB, were injected into tumor-bearing mice." (PMID 24998519, 2014). "Addition of the cytoplasmic domain of CD28, CD134 or CD137 to CD3-ζ-containing CARs can lead to increased cytokine production in response to tumor-associated antigens (TAA) and an enhanced ability of adoptively transferred T cells to mediate tumor regression." (PMID 25505964, 2014). "Upon initial activation by antigen-presenting cells (APCs), tumor-specific T cells receive essential co-stimulation through binding of CD28 to CD80/86 on activated APCs." (PMID 24855562, 2014).
tumor (continued). "Exposure to IL-21 during in vitro priming has previously been shown to enrich for a population of CD8+ T cells with high affinity recognition of tumor antigen, effector function, and expression of co-stimulatory molecules such as CD28." (PMID 25317334, 2014). "Sequential stimulation of T cells with DC/tumor fusions and ligation of the T cell costimulatory complex with anti-CD3/CD28 results in the dramatic expansion of tumor-specific lymphocytes." (PMID 25386340, 2014). "The enhanced T-cell based immune response against RMA-S/B7-1 cells occurs at the effector phase of the immunity and requires binding of B7-1 on tumor cells to CD28 on antigen specific T effectors." (PMID 25383875, 2014). "We further showed that these senescent T cells significantly down-regulated expression of co-stimulatory molecule CD28, suggesting dysfunction of these tumor-infiltrating T cells." (PMID 25231413, 2014). "Yet, REM has been shown to greatly reduce CD28 and CD27 expression of the expanded TIL, and this is associated with reduced persistence and subsequent limited anti-tumor activity of the infused TIL." (PMID 23402380, 2013). "Ex vivo expansion of TIL with the IL-2-based systems greatly reduces CD27 and CD28 expression, resulting in reduced persistence and subsequent limited anti-tumor activity in vivo." (PMID 23402380, 2013). "We combined the well-established anti-CD3 and anti-CD3/CD28 mAb triggered T-cell stimulation with isolated tumor cell line-derived CEACAM-positive MVs or CHO/CHO-CEACAM1 derived MVs." (PMID 24040308, 2013). "Despite its potential, REM has been shown to greatly reduce CD28 and CD27 expression on the expanded TIL, and this is associated with reduced persistence and hence limited anti-tumor activity of the infused TIL." (PMID 23402380, 2013). "BM-derived IMCs from non- tumor bearing mice and MDSCs from tumor-bearing mice were co-cultured with CFSE-labeled splenocytes in the presence of anti CD3/CD28 Dynabeads, and T-cell proliferation analyzed by flow cytometry after 5 days of culture." (PMID 23843936, 2013). "In contrast to the robust proliferation of Tim-3− counterparts, tumor-derived Tim-3+CD4 T cells were anergic to anti-CD3/CD28 stimulation, characteristics shared by “classical” human Treg cells." (PMID 23526963, 2013). "We have presented data demonstrating the robust anti-tumor activity of T cells genetically modified to express a CD20-CAR that contains CD28 and 41BB co-stimulatory domains, and a CD3ζ endodomain." (PMID 24358223, 2013). "For instance, human tumor-infiltrating CD8+/CD28- regulatory T cells secrete IL-10, TNF-α, and IFN-γ, express FOXP3, and suppress the proliferation of CD8+ effector T cells." (PMID 23272178, 2012). "Similar approaches were tested for tumor vaccines using fusion of CTLA-4 or CD28 and tumor antigens to enhance specific immunity to tumor antigens." (PMID 21799884, 2011). "A recent study identified circulating and tumor-infiltrating CD28+CD8+ Tregs with a CD25+, FOXP3+, CD152+, GITR+, CD194+, TGF-β+, and CD127− phenotype." (PMID 22110523, 2011). "A recent study identified circulating and tumor infiltrating CD28+ CD8+ Tregs with a CD25+, FOXP3+, CTLA-4+, GITR+, CCR4+, TGF-β+ and CD127low/neg phenotype." (PMID 24212779, 2011). "Based on the present study, we conclude incorporation of co-stimulation via NKG2D along with CD28 is essential and obligatory to stimulate tumor or tissue-infiltrating effector CD8+ T cells." (PMID 20844584, 2010). "Next, tumor-specific CTLs were stimulated with CD3 mAb in the presence of a co-stimulation signal (CD28 mAb) or with the cognate Ag (tumor cells) and analyzed for tumor rejection efficacy in vivo." (PMID 21124930, 2010). "B7-1-transduced tumour cells are expected to present both the antigen and the co-stimulatory (CD28-mediated) signals to CD8+ CTL simultaneously, leading to efficient activation of CTLs without requiring the assistance of CD4+ helper T cells." (PMID 21172020, 2010).